AKAP13 (A-kinase anchoring protein 13)
Description:
Scaffold protein that plays an important role in assembling signaling complexes downstream of several types of G protein-coupled receptors. Activates RHOA in response to signaling via G protein-coupled receptors via its function as Rho guanine nucleotide exchange factor. May also activate other Rho family members. Part of a kinase signaling complex that links ADRA1A and ADRA1B adrenergic receptor signaling to the activation of downstream p38 MAP kinases, such as MAPK11 and MAPK14. Part of a signaling complex that links ADRA1B signaling to the activation of RHOA and IKBKB/IKKB, leading to increased NF-kappa-B transcriptional activity. Part of a RHOA-dependent signaling cascade that mediates responses to lysophosphatidic acid (LPA), a signaling molecule that activates G protein-coupled receptors and potentiates transcriptional activation of the glucocorticoid receptor NR3C1. Part of a signaling cascade that stimulates MEF2C-dependent gene expression in response to lysophosphatidic acid (LPA) (By similarity). Part of a signaling pathway that activates MAPK11 and/or MAPK14 and leads to increased transcription activation of the estrogen receptors ESR1 and ESR2. Part of a signaling cascade that links cAMP and EGFR signaling to BRAF signaling and to PKA-mediated phosphorylation of KSR1, leading to the activation of downstream MAP kinases, such as MAPK1 or MAPK3. Functions as a scaffold protein that anchors cAMP-dependent protein kinase (PKA) and PRKD1. This promotes activation of PRKD1, leading to increased phosphorylation of HDAC5 and ultimately cardiomyocyte hypertrophy (By similarity). Has no guanine nucleotide exchange activity on CDC42, Ras or Rac. Required for normal embryonic heart development, and in particular for normal sarcomere formation in the developing cardiomyocytes (By similarity). Plays a role in cardiomyocyte growth and cardiac hypertrophy in response to activation of the beta-adrenergic receptor by phenylephrine or isoproterenol. Required for normal adaptive cardiac hypertrophy in response to pressure overload. Plays a role in osteogenesis (By similarity).
Synonyms: AKAP-13; PRKA13; BRX; HT31; LBC; AKAP-Lbc; c-lbc; PROTO-LB; HA-3; ARHGEF13; PROTO-LBC; p47
Tractability: Small molecule: a structure with a bound ligand is known. Antibody: UniProt places it where antibodies can reach, with high confidence. PROTAC: ubiquitination databases record sites on it; its protein half-life has been measured.
Gene: Protein-coding gene on chromosome 15 (85,380,571 to 85,749,358, forward strand). Ensembl gene ENSG00000170776.
Subcellular location: Cytoplasm, cytosol; Cytoplasm; Cytoplasm, cell cortex; Nucleus; Membrane
Subcellular location (Human Protein Atlas): Cytosol
Pathways (Reactome):
Signal Transduction: G alpha (12/13) signalling events; NRAGE signals death through JNK; RHOA GTPase cycle; RHOB GTPase cycle; RHOC GTPase cycle
Gene Ontology:
Molecular function: guanyl-nucleotide exchange factor activity; MAP-kinase scaffold activity; molecular adaptor activity; protein binding; protein kinase A binding; small GTPase binding
Biological process: adrenergic receptor signaling pathway; G protein-coupled receptor signaling pathway; positive regulation of canonical NF-kappaB signal transduction; positive regulation of Rho protein signal transduction; bone development; cardiac muscle cell differentiation; heart development; positive regulation of MAPK cascade; regulation of sarcomere organization; regulation of small GTPase mediated signal transduction; small GTPase-mediated signal transduction; MAPK cascade; regulation of intracellular signal transduction
Cellular component: cell cortex; cortical actin cytoskeleton; cytoplasm; cytosol; membrane; nucleus; actin cytoskeleton
Genetic constraint (gnomAD): Loss-of-function variants: 75 observed, 251.27 expected, observed/expected ratio (o/e) 0.3, 90% interval 0.25 to 0.36. The upper end of that interval is the gene's LOEUF score, 0.36, which puts it in group 1 of 6, group 1 being the genes least tolerant of losing a copy. Missense variants: 3,594 observed, 3,482.8 expected, observed/expected ratio (o/e) 1.03, 90% interval 1 to 1.06. Synonymous variants: 1,340 observed, 1,275.3 expected, observed/expected ratio (o/e) 1.05, 90% interval 1 to 1.1.
Homologues: Orthologues: chimpanzee AKAP13 (98% identical), macaque AKAP13 (94% identical), dog AKAP13 (75% identical), mouse Akap13 (73% identical), rat Akap13 (73% identical), tropical clawed frog akap13 (15% identical), zebrafish arhgef28b (10% identical).
Diseases named in the same sentence as AKAP13 in open-access papers:
AKAP13 is named in the same sentence as 42 diseases in open-access papers, as found by Europe PMC text mining. Sharing a sentence is not in itself a finding about the gene and the disease. The quoted sentences say what the papers report.
cardiac hypertrophy (13 papers, 2014 to 2023). "The AKAP13 expression level rises in response to cardiac stress and acts as an early modulator of compensatory cardiac hypertrophy." (PMID 33923648, 2021). "The RhoGEF (Rho GTPase guanine-nucleotide-exchange factor) domain of AKAP-Lbc (A-kinase-anchoring protein-Lbc, also known as AKAP13) catalyses nucleotide exchange on RhoA and is involved in the development of cardiac hypertrophy." (PMID 25186459, 2014). "Genes associate with cardiac hypertrophy included JMJD1C, ANXA7, TRIM8, NGB, and AKAP13." (PMID 36071494, 2022). "Microarray analysis showed that AKAP13-ΔPKD1 mice broadly failed to exhibit the transcriptional profile normally associated with compensatory cardiac hypertrophy following trans-aortic constriction (TAC)." (PMID 26192751, 2015). "A-Kinase Anchoring Protein 13 (AKAP13) promotes downstream hypertrophic gene expression, mediated at least in part via HDAC5 phosphorylation and MEF2-mediated transcription in a transverse aortic constriction (TAC) model of cardiac hypertrophy." (PMID 36656640, 2023).
breast carcinoma (12 papers, 2012 to 2023). "The dysregulation and mutation of AKAP13 were found to be associated with the progression of colorectal cancer and breast cancer." (PMID 31787999, 2019). "The polymorphisms R494W, K526Q, N1086D, and G2461S in AKAP13 were all found in familial breast cancer patients with K526Q having the highest association among all of these SNPs." (PMID 29370121, 2018). "Specific polymorphisms in AKAP10 and in particular in combination with a SNP in AKAP13 were shown to be associated with increased risk for familial breast cancer." (PMID 29433456, 2018). "A polymorphism in AKAP13 (Lys526Gln) has been described to correlate with high-risk familial breast cancer." (PMID 26272591, 2015). "AKAP13 plays a major role in PKA-induced phosphorylation of ER, which is a significant cause of tamoxifen resistance in breast cancer cells and cancer patients." (PMID 35042833, 2022). "AKAP13 expression levels correlated with a poor outcome after tamoxifen treatment in breast cancer patients and correlated with ERαS305 phosphorylation status." (PMID 26272591, 2015). "Breast cancer stratification on ERαS305 phosphorylation status led to the identification of AKAP13 as a potential mediator for this phosphorylation event on ERα." (PMID 26272591, 2015). "In a luminal breast cancer cell line, AKAP13 was found to interact with ERα as well as with a regulatory subunit of PKA." (PMID 26272591, 2015). "We show that the PKA-anchoring protein AKAP13 is essential for the phosphorylation of ERαS305, which leads to tamoxifen resistance both in cell lines and tamoxifen-treated breast cancer patients." (PMID 26272591, 2015). "If AKAP13 is indeed required for the PKA-mediated Serine 305 phosphorylation in breast cancer patients, the expression levels of AKAP13 would be expected to correlate with ERαS305P positivity." (PMID 26272591, 2015). "Among these SNPs, several are relevant to disorders common in Qataris, including type 2 diabetes (UTS2), breast cancer (AKAP13), hypertension (ULK4), and nicotine dependence (FMO2)." (PMID 23139751, 2012). "Additionally, upregulation of CA2, CNN3 and AKAP13 was found, which are suggested to be involved in chemotherapy resistance in glioblastoma, colon cancer and breast cancer, respectively." (PMID 33712646, 2021). "We furthermore identified upregulation of the direct EZH2 target genes CNN3 and AKAP13, that are involved in chemotherapy resistance in colon cancer and breast cancer, respectively, and the genes MYO5A, AKT3 and SPECC1, which are implicated in the evasion of apoptosis." (PMID 33712646, 2021). "Furthermore, the AKAP13 K526Q SNP, along with I646V in AKAP10, further augmented the risk for breast cancer." (PMID 29370121, 2018). "A number of these AKAPs have been reported to correlate with the occurrence of different cancer subtypes, including AKAP3 (ovarian cancer), AKAP4 (multiple myeloma), AKAP9 (breast cancer), AKAP10 (breast cancer) and AKAP13 (colorectal cancer and breast cancer)." (PMID 26272591, 2015). "Next, we investigated whether AKAP13 levels by themselves correlate with an unfavorable response to treatment in breast cancer patients." (PMID 26272591, 2015). "siRNA-mediated knockdown of AKAP13 and AKAP95 was performed in MCF-7 breast cancer cells (respectively)." (PMID 26272591, 2015). "In the studied cohort of breast cancer patients, we found AKAP95 as well as AKAP13 signaling pathways significantly enriched in the ERαS305P positive subpopulation." (PMID 26272591, 2015).
Alzheimer disease (3 papers, 2018 to 2026). A progressive, neurodegenerative disease characterized by loss of function and death of nerve cells in several areas of the brain leading to loss of cognitive function such as memory and language. "AKAP13 are likely more specifically involved in tau phosphorylation pathways that is highly related to Alzheimer’s disease." (PMID 29653596, 2018). "In replication analyses, 21 genes showed nominal support in UK Biobank and Alzheimer's Disease Genetics Consortium (ADGC) cohorts, with eight genes (TREM2, ACADS, MFSD12, NUP210L, PIEZO2, PSEN1, SMURF2, AKAP13) supported under identical masks." (PMID 41960309, 2026).
idiopathic pulmonary fibrosis (3 papers, 2021 to 2025). Idiopathic pulmonary fibrosis (IPF) is a nonneoplastic pulmonary disease that is characterized by the formation of scar tissue within the lungs in the absence of any known cause. "A polymorphism near the AKAP13 gene, associated with increased levels of AKAP13 mRNA expression in the lung, was reported to be associated with an increased risk of developing idiopathic pulmonary fibrosis (IPF)." (PMID 40650217, 2025). "A previous study revealed that AKAP13 was expressed in the alveolar epithelium and lymphoid follicles of patients with idiopathic pulmonary fibrosis, and AKAP13 mRNA expression was higher in lung tissue of patients with IPF than that in lung tissue from controls." (PMID 35819256, 2022).
heart failure (2 papers, 2015 to 2022). Inability of the heart to pump blood at an adequate rate to meet tissue metabolic requirements. "Ablation of the AKAP13-PKD1 binding domain (AKAP13-∆PKD1) leads to a diminished hypertrophic response in a mouse model for heart failure (i.e. TAC or Angiotensin II)." (PMID 26192751, 2015).
hepatocellular carcinoma (2 papers, 2019 to 2022). A malignant tumor that arises from hepatocytes. "Meanwhile, AKAP3 and AKAP13 may be potential biomarkers for the diagnosis and prognosis of hepatocellular carcinoma." (PMID 31384238, 2019). "AKAP13 is expressed increasingly in hepatocellular carcinoma, but it is not expressed in healthy adult liver." (PMID 35042833, 2022).
lung adenocarcinoma (2 papers, 2021 to 2023). A carcinoma that arises from the lung and is characterized by the presence of malignant glandular epithelial cells. "AKAP13 expression correlates with mTORC1 activation and overall lung adenocarcinoma patient survival, as well as lung cancer tumor growth in vivo." (PMID 34673774, 2021). "Furthermore, the degree of AKAP13 expression in lung adenocarcinoma cell lines correlates with mTORC1 activity." (PMID 36734879, 2023).
lung carcinoma (2 papers, 2021 to 2022). "Consistently, lung cancer cells (H2887, A549) with high AKAP13 expression formed less colonies than lung cancer cells (DFC1032, H2126) with low AKAP13 expression." (PMID 34673774, 2021). "Importantly, AKAP13 plays a key role in mTORC1-mediated biology and the overall survival of lung cancer patients." (PMID 34673774, 2021).
melanoma (2 papers, 2016 to 2023). A malignant, usually aggressive tumor composed of atypical, neoplastic melanocytes. "NDC80, PLCE1 and AKAP13 have so far not been studied in melanoma." (PMID 27853253, 2016).
prostate carcinoma (2 papers, 2021 to 2022). A carcinoma that arises from epithelial cells of the prostate gland. "miRNA-629-5p plays an oncogenic role by promoting prostate cancer development and metastasis by targeting A-kinase anchor protein 13 (AKAP13)." (PMID 35457012, 2022).
acute myeloid leukaemia (1 paper, 2022). "Another study claimed that AKAP13 expression knockdown suppressed the proliferation and invasion of acute myeloid leukaemia cells." (PMID 35390056, 2022).
blast crisis (1 paper, 2021). "AKAP13 (i.e., AKAP-lymphoid blast crisis (AKAP-Lbc) or Ht31) is a PKA type II-specific anchoring protein expressed in the cytoplasm of cardiac fibroblasts and cardiomyocytes." (PMID 33923648, 2021).
breast tumors (1 paper, 2015). "Stratifying breast tumors on ERα Serine 305 phosphorylation status resulted in the identification of a gene network centered upon AKAP13." (PMID 26272591, 2015). "In addition, AKAP13 mRNA levels correlate with ERαSerine 305 phosphorylation in breast tumor samples, suggesting a functional connection between these two events." (PMID 26272591, 2015).
fibrosis (1 paper, 2019). the formation of excess fibrous connective tissue in an organ or tissue in a reparative or reactive process. "Based on previous findings showing that AKAP13 recruits and activates the MAPK p38 and that p38 acts as a major mediator of the profibrotic effects of Ang-II, one could raise the hypothesis that AKAP13 might regulate cardiac fibrosis by promoting p38 signaling in cardiac fibroblasts." (PMID 31888098, 2019).
osteoporosis (1 paper, 2023). A condition of reduced bone mass, with decreased cortical thickness and a decrease in the number and size of the trabeculae of cancellous bone (but normal chemical composition), resulting in increased fracture incidence. "It has been shown that the AKAP13 gene affects heart development in mice, and bone formation and AKAP13 deficiency can lead to osteoporosis and abnormal heart development." (PMID 37685010, 2023).
viral myocarditis (1 paper, 2025). Myocarditis that is caused by an infection with a viral agent. "A pathway enrichment analysis highlighted pathways such as viral myocarditis, Rho-selective guanine exchange factor AKAP13 signaling, and lipid metabolism." (PMID 40650217, 2025).
cancer (14 papers, 2007 to 2025). A tumor composed of atypical neoplastic, often pleomorphic cells that invade other tissues. "Genetic variation and expression of AKAP13, a protein kinase, is associated to regulation of cancer and response to cardiac hypertrophy." (PMID 30644396, 2019). "The AKAP13 gene, located in human chromosome 15, is reported to be involved in the pathogenesis of various cancers, including NSCLC." (PMID 36011391, 2022). "AKAP13 mutations were associated with the progression of several cancers; however, no prior study examined the association between AKAP13 mutations and BCG outcomes." (PMID 35311085, 2022). "Next, we tested if a phospho-mimetic of Raptor Ser 791 (HA-tagged Raptor Ser 791 to Asp 791, HA-tagged Raptor S791D) could affect cell proliferation and size in AKAP13 KO or LUAD cancer cells." (PMID 34673774, 2021). "Disruption of AKAP13 mediated anchoring of PKA decreased carcinoma cell line migration in vitro." (PMID 29433456, 2018). "There are several publications relating the A-kinase anchoring protein AKAP13 and cancer." (PMID 19455237, 2007). "Among these proteins, AKAP4 and AKAP9 have been extensively studied as cancer-promoting factors, whereas AKAP12 and recently AKAP13 have been shown to play the opposite role, although their mechanism of action has not been studied in depth." (PMID 36203781, 2022). "Four different LUAD cancer cell lines (DFCI032, H2126, H2887 and A549) were utilized to analyze AKAP13 protein level and mTORC1 activity." (PMID 34673774, 2021). "In addition to LUAD cells we also observed a decrease in mTORC1 activity (as measured by the phosphorylation of S6) when AKAP13 was overexpressed in prostate (PC3) and liver (Huh7) cancer cells." (PMID 34673774, 2021).
tumor (10 papers, 2013 to 2025). "The GNAS p.(Arg844Cys) mutation, as well as variants of uncertain significance AKAP13 p.(His641Pro) and EPAS1 p.(Ser478del) were detected in the tumor." (PMID 40175770, 2025). "In the present study, in addition to exploring the biological function of miR-629-5p as a key miRNA, we further confirmed that its mechanism is to promote the growth and metastasis of PCa by targeting inhibition of AKAP13, a tumor suppressor." (PMID 34722307, 2021). "More precisely, the function of miR-629-5p tumor-promoting effect is realized by targeting AKAP13, which provides a new idea for clinical diagnosis and treatment of complex refractory PCa." (PMID 34722307, 2021). "AKAP13 high tumours were more often lymph node positive (p = 0.033) and there was a trend towards negative progesterone receptor status (p = 0.071)." (PMID 26272591, 2015). "Time to tumor progression (TTP) was estimated according to the Kaplan–Meier method for AKAP13 expression, segmenting the continuous variable in two groups (low and high) with equal numbers of patients." (PMID 26272591, 2015). "According to a recent study, AKAP13 was regarded as a new tumor suppressor in PCa, which could prevent tumor invasion in collaboration with PTEN." (PMID 34722307, 2021). "More importantly, the silence of AKAP13 expression could reverse the tumor suppressor function of miR-629-5p inhibitor in PCa cells." (PMID 34722307, 2021). "Finally, the potential value of AKAP13 as a tumor suppressor gene was verified in clinical data." (PMID 34722307, 2021). "Interestingly, in cells with AKAP13 depletion the tumor volume was significantly increased." (PMID 34673774, 2021). "Pathway analyses indicated a difference in inflammatory response between the two primary tumours, with upregulation of OAS2, CCL2, and AKAP13 in Patient 1 compared to Patient 2 across all cell populations." (PMID 40438247, 2025). "Moreover, A-kinase Anchor Protein 13 (AKAP13) was screened as a direct target of miR-629-5p, that expression was negatively correlated with the malignant phenotype of tumor cells." (PMID 34722307, 2021). "Through the detection of AKAP13 protein in prostate related cell lines, high-level expression in RWPE-1 indicates that it might be a potential tumor suppressor gene." (PMID 34722307, 2021).
adenocarcinoma (1 paper, 2015). A common cancer characterized by the presence of malignant glandular cells. "For adenocarcinoma specifically, DM was observed in promoters [hypermethylated RASL12; SPTAN1, mir-26a, hypomethylated NQO1, SIRPB1, NF1A] and gene bodies [hypermethylated AKAP13, ANK family, PRKCE, ROS1; hypomethylated FAM171A1, PARK2, BCAS3, RHOJ] and many others." (PMID 26683690, 2015).
AKAP13 also shares sentences with these, for which no sentence is quoted: dementia (2 papers); endometrial cancer (2); influenza (2); asthma (1); autism spectrum disorder (1); botulism (1); colon cancer (1); colorectal cancer (1); gastric cancer (1); glioblastoma (1); Hypertension (1); idiopathic interstitial pneumonia (1); infection (1); Infertility (1); Insulin resistance (1); iron deficiency (1); nicotine dependence (1); ovarian carcinoma (1); ovarian tumors (1); pancreatic cancer (1); pulmonary arterial hypertension (1); swine influenza (1); type 2 diabetes (1).